CRP (C-reactive protein)
Diseases named in the same sentence as CRP in open-access papers (continued):
Sharing a sentence is not in itself a finding about the gene and the disease.
inflammatory bowel disease (continued). "Here, we studied agreement between a novel POCT device and reference methods of measuring infliximab (IFX) and adalimumab (ADL) serum concentrations and C-reactive protein (CRP) and faecal calprotectin (FCP) concentrations of patients with inflammatory bowel disease (IBD)." (PMID 37238198, 2023). "Regardless of symptoms, serum C-reactive protein levels were not a reliable indicator of controlled inflammatory bowel disease." (PMID 35584442, 2022). "Regardless of symptoms, serum levels of C-reactive protein were not a useful marker of controlled inflammatory bowel disease." (PMID 35584442, 2022). "In inflammatory bowel disease (IBD), OSM and its receptor (OSMR) are expressed in high levels in inflamed intestinal tissue, and levels are correlated with histopathological disease severity and CRP levels." (PMID 30621017, 2019). "Adding other potential confounding variables to the model (CRP, inflammatory back pain, HLA-B27, inflammatory bowel disease) did not change the results." (PMID 29490705, 2018). "We demonstrate that this device can be used to detect C-reactive protein (CRP)—a biomarker for neonatal sepsis, pelvic inflammatory disease, and inflammatory bowel diseases—at a concentration range of 1–100 ng/mL in 1000-fold diluted blood (1–100 μg/mL in undiluted blood)." (PMID 28738231, 2018). "Interestingly, determination CRP and PCT together was superior to CRP alone for diagnosing active or severe inflammatory bowel diseases." (PMID 23207551, 2013). "Due to elevated fecal calprotectin and C-reactive protein (CRP), an initial working diagnosis of inflammatory bowel disease (IBD) was considered." (PMID 40823575, 2025). "IQR: interquartile range; IBD: inflammatory bowel disease; CRP: C-reactive protein; SUVmax: standardized uptake value maximum." (PMID 40007923, 2025). "Additionally, we examined the therapeutic effect of ginsenosides by assessing the Canine Inflammatory Bowel Disease Activity Index (CIBDAI), C-reactive protein (CRP) levels, colonic tissue morphology, protein expression, and mucosal bacterial community analysis." (PMID 38004628, 2023). "In patients with active inflammatory bowel disease, serum ghrelin concentrations are significantly elevated and positively correlated with serum inflammatory markers, such as tumor necrosis factor-α (TNF-α), C-reactive protein (CRP), erythrocyte sedimentation rate (ESR) and fibrinogen." (PMID 36350879, 2022). "Thus, we were supposed to take the Mayo score, SDI, Inflammatory Bowel Disease Questionnaire (IBDQ), and C-reactive protein (CRP) of pre- or post-FMT into account, and the FMT route of administration and donor selection were also considered for analysis." (PMID 29849592, 2018). "Markers based on systemic inflammation, such as C-reactive protein (CRP), TNFα, interleukin-6, or white blood cell (WBC) count have been reported to be useful in predicting the prognosis in patients with inflammatory disease including inflammatory bowel disease." (PMID 28076386, 2017). "The authors indicated that higher SIRI levels were significantly correlated with active inflammatory bowel disease (IBD), CRP, ESR, NLR, and MLR, and might be a novel promising marker of the disease severity in IBD." (PMID 38137357, 2023). "In human medicine, the C-reactive protein-albumin ratio (CRP/ALB) has been used in emergency medicine, oncology and gastroenterology, with a high discriminative capacity for active inflammatory bowel disease (IBD)." (PMID 36766371, 2023). "Although TDM can be regarded to be intuitively built on treat-to-target strategies (Selecting Therapeutic Targets in Inflammatory Bowel Disease (STRIDE) Initiative) in IBD, which include clinical improvement, mucosal healing, or normalization of CRP, TDM is not included in these parameters." (PMID 40002904, 2025). "A raised CRP is not specific to gastrointestinal inflammation; and a raised FCP is not specific to inflammatory bowel disease." (PMID 37540200, 2024).
inflammatory bowel disease (continued). "Regarding the inflammatory status, CRP is one of the most widely used serum markers of inflammation in inflammatory bowel disease (IBD), but it is not disease specific, since elevated levels occur in several inflammatory disorders not related to the gastrointestinal tract." (PMID 37111172, 2023).
Neonatal sepsis (190 papers, 2007 to 2026). Systemic inflammatory response to infection in newborn babies. "Background: some consensus guidelines include C-reactive protein (CRP) in the diagnostic workup of early-onset neonatal sepsis (EOS), but its routine use remains debated due to variable diagnostic performance." (PMID 41892467, 2026). "Limitations of CRP: CRP is a widely used biomarker in the detection of neonatal sepsis; however, some limitations reduce its diagnostic accuracy in the early detection of neonatal sepsis." (PMID 40970024, 2025). "The purpose of this systematic review is to answer, using evidence-based research, the following question: How do PCT and CRP compare in their diagnostic accuracy and clinical utility for the early diagnosis of neonatal sepsis?" (PMID 40970024, 2025). "In view of this controversy, a more thorough review encompassing the latest literature is warranted to compare the diagnostic accuracy of RETN levels with that of CRP levels in diagnosing paediatric and neonatal sepsis." (PMID 40416430, 2025). "To address this, and based on the evidence analyzed in this systematic review, we developed a clinical decision-making flowchart, which illustrates a potential application of PCT alongside CRP in the diagnostic evaluation of neonatal sepsis." (PMID 40970024, 2025). "The C-reactive protein (CRP) level has gained importance as a laboratory test in managing neonatal sepsis, as it has been found to help in diagnostic and prognostic evaluation." (PMID 39006693, 2024). "Preterm babies admitted to NICU, grunting, meconium amniotic stained (MSAF), duration of rupture of membrane >18hours (PROM), Hypertensive PIH/ Eclampsia, meropenum and CRP result were significantly associated with poor treatment outcome of neonatal sepsis." (PMID 37252936, 2023). "Beyond its use as diagnostic marker, CRP is particularly useful in monitoring the response to treatment and is used to guide the antibiotic therapy in neonatal sepsis." (PMID 35345614, 2022). "Interleukin 6 (IL-6), associated with C-reactive protein (CRP), plays an essential diagnostic role in neonatal sepsis in premature newborns and is associated as a prognostic marker of late neonatal sepsis." (PMID 36355884, 2022). "An interesting metanalysis compared the diagnostic accuracy of PCT, CRP, procalcitonin combined with C-reactive protein and presepsin in the diagnosis of neonatal sepsis, including 28 studies in which 2661 patients were enrolled." (PMID 34830040, 2021). "In the previous studies, the optimal cut-off values of IL-6 and CRP are defined inconsistently, and their diagnostic performance for identification of neonatal sepsis varies." (PMID 33233806, 2020). "In the current study, we tried to see the diagnostic significance of White Blood Cell (WBC) count and CRP in diagnostic screening of neonatal sepsis." (PMID 30069260, 2018). "Based on this study’s finding, it can be concluded that CRP alone or in combination with WBC count showed better diagnostic accuracy in neonatal sepsis." (PMID 30069260, 2018). "Most previous studies have established that CRP is a useful diagnostic test for the early stages of neonatal sepsis reaching a peak during the first 24-48 hours with better sensitivity and specificity." (PMID 30069260, 2018). "Current diagnostic tests for neonatal sepsis, such as blood count indices and serum C-reactive protein (CRP), have poor sensitivity and specificity and thus limited utility." (PMID 28045978, 2017). "Over all the diagnostic accuracy of CRP in diagnosis of neonatal sepsis was 70.07%, as shown in Table-III." (PMID 26150837, 2015). "The CRP was able to correctly identify all cases (100.0%) of neonatal sepsis caused by Escherichia coli, Proteus spp, Enterococcus spp, Staphylococcus epidermidis and Streptococcus spp." (PMID 22958461, 2012). "As infection is the most likely cause of inflammation in the neonate, CRP has been shown to be useful in the diagnosis of neonatal sepsis." (PMID 22958461, 2012).
Neonatal sepsis (continued). "Among the risk factors for neonatal sepsis, CRP performance was highest in neonates born to mothers with foul smelling amniotic fluid, followed by peri-partum pyrexia." (PMID 22958461, 2012). "The latest Cochrane review suggested that CRP alone may lack sufficient accuracy as a diagnostic tool for neonatal sepsis." (PMID 39825283, 2025). "WBC has been shown to have a neonatal sepsis diagnostic performance similar to CRP." (PMID 39201833, 2024). "Additionally, serum ferritin seems to be a more accurate indicator of neonatal sepsis mortality risk than CRP." (PMID 38793057, 2024). "However, although the diagnostic value of YKL-40 in neonatal sepsis is substantial, it was found to be inferior to the diagnostic value of CRP in this study." (PMID 37238320, 2023). "Even if the literature supports the use of rapid methods with high sensitivity and specificity (Cytokines, PCR based methods) or the use of calculators such as Kaiser Permanente EOS, blood culture is still the standard of care for detecting neonatal sepsis in association with CRP or PCT." (PMID 34572631, 2021). "Elevated C-reactive protein was significantly associated with neonatal sepsis (p = 0.001)." (PMID 34706677, 2021). "Over all the diagnostic accuracy of CRP in diagnosis of neonatal sepsis was 70.07%." (PMID 26150837, 2015). "Meta-analysis results showed that the pooled sensitivity of IL-27 for diagnosing neonatal sepsis was 0.82 [95% confidence interval (CI), 0.77-0.87], which was significantly higher than that of CRP (0.73; 95% CI, 0.65-0.79)." (PMID 42212107, 2026). "In this study, NeoSep-SAA significantly out-performed the currently available gold-standard biomarker, CRP, for neonatal sepsis detection (p<0.0001, 95% CI)." (PMID 39937751, 2025). "C-reactive protein (CRP) is a biochemical inflammation marker, and blood (serum or plasma) CRP is often used in early-onset neonatal sepsis (EOS) diagnostics." (PMID 41441318, 2025). "This study aimed to compare the diagnostic accuracy of RETN levels with that of C-reactive protein (CRP) levels in the diagnosis of paediatric and neonatal sepsis through a comprehensive review of recent literature." (PMID 40416430, 2025). "Advantages of CRP: Despite its known limitations, CRP remains a valuable tool in the diagnosis of neonatal sepsis due to its simplicity, rapid turnaround time, low cost, and widespread availability." (PMID 40970024, 2025). "Even so, CRP is the most commonly used marker in neonatal sepsis (early or late), although it has limitations and can lead to false positive or false negative results in clinical practice." (PMID 40150637, 2025). "Alpha1AG, the best predictive marker in this study, is a stronger early predictor of mortality in neonatal sepsis than CRP." (PMID 40075818, 2025). "This systematic review suggested the following future directions for the use of CRP in diagnosing neonatal sepsis." (PMID 40970024, 2025). "NeoSep-SAA showed superior sensitivity for neonatal sepsis over C-Reactive Protein detection (sensitivity: 37%), albeit with some sacrifice of specificity." (PMID 39937751, 2025). "While CRP and PCT are widely used in clinical practice, they have limitations in early diagnostic accuracy, particularly for neonatal sepsis." (PMID 40123668, 2025). "NLR levels have been shown to be elevated in PPROM cases and have similar predictive power to white blood cell count and CRP in predicting neonatal sepsis and histologic chorioamnionitis." (PMID 40428181, 2025). "The biomarker's rapid elevation within 2–4 h of infection offers a temporal advantage over CRP (typically rising after 6–8 h), enabling earlier antibiotic decisions in time-sensitive scenarios like paediatric and neonatal sepsis." (PMID 40416430, 2025). "CRP is a widely used acute-phase reactant in the diagnosis of neonatal sepsis due to its easy accessibility, low cost, and rapid results." (PMID 40564645, 2025).
Neonatal sepsis (continued). "C-reactive protein (CRP) is the most frequently used laboratory biomarker to assist in detecting neonatal sepsis." (PMID 40970024, 2025). "CRP can be influenced by several factors, which can impact its accuracy in detecting neonatal sepsis." (PMID 40970024, 2025). "Our study further confirms these associations and highlights PCT’s emerging role as a more sensitive early biomarker than traditional markers such as CRP, consistent with previous publications on neonatal sepsis biomarkers." (PMID 41010644, 2025). "PCT can be affected by non-infectious conditions stated previously under "Accuracy of C-reactive Protein in Diagnosing Neonatal Sepsis"." (PMID 40970024, 2025). "CRP is frequently used as a supportive marker in the diagnosis of neonatal sepsis and is often relied upon in ambiguous cases, despite its lack of specificity." (PMID 41009903, 2025). "Procalcitonin (area under the curve—AUC = 0.78) and CRP (AUC = 0.76) measured on the first day had the best predictive performance for early-onset neonatal sepsis." (PMID 38255436, 2024). "This study aimed to evaluate the correlation between CRP, blood culture, and neonatal sepsis in the NICU at Atbara Teaching Hospital (ATH), Sudan." (PMID 38654771, 2024). "The interrelationship of serum CRP, platelet counts, and other haematological parameters has been an area of interest in recent research studies in neonatal sepsis diagnosis and management." (PMID 39006693, 2024). "Our results showed that procalcitonin (AUC: 0.78) and CRP measured on the first day (AUC: 0.76) had the best predictive performance for early-onset neonatal sepsis when taken individually." (PMID 38255436, 2024). "CRP begins to rise between 8–12 h and peaks at 24–48 h after infection onset, so, due to its delayed rise as a response to infection, CRP has an unacceptable low sensitivity within the first 24 h for the early diagnosis of neonatal sepsis." (PMID 39858292, 2024). "This, together with a well described delayed increase in CRP-levels at the occurrence of an infection, makes CRP as a biomarker unreliable for early detection of neonatal sepsis." (PMID 38517573, 2024). "Presepsin has been shown in meta-analyses to be as accurate as procalcitonin (PCT) and C-reactive protein (CRP) in diagnosing neonatal sepsis." (PMID 39858292, 2024). "C-reactive protein (CRP) level in serum and platelet counts have been reported to have role in diagnosis of neonatal sepsis." (PMID 39006693, 2024). "Serum CRP is well recognized as one of the major biomarkers for the diagnosis of early onset neonatal sepsis (EOS)." (PMID 38302903, 2024). "This suggests that HBP is superior to PCT and hs-CRP in the early diagnosis and clinical grading of neonatal sepsis." (PMID 39193501, 2024). "CRP is one of the most frequently used acute-phase reactants in the diagnosis and treatment response of neonatal sepsis." (PMID 39457173, 2024). "Currently, C-reactive protein (CRP) is the most studied biomarker, and in a recent meta-analysis of CRP for neonatal sepsis, the pooled sensitivity was 0.74 and specificity was 0.62." (PMID 37181361, 2023). "Several earlier researchers have found a positive correlation between salivary and serum CRP, advocating using salivary CRP as a screening tool for neonatal sepsis." (PMID 36900011, 2023). "ROC curve analysis depicted the better discriminatory capability of LCR in contrast with lymphocyte count and CRP in identifying neonatal sepsis." (PMID 37197571, 2023). "The AUC for LCR in identifying neonatal sepsis was 0.70 (95% CI, 0.67–0.73, p < 0.001), which was higher than the AUC for lymphocyte count (AUC = 0.60, 95% CI, 0.57–0.63, p < 0.001) and CRP (AUC = 0.66, 95% CI, 0.63–0.69, p < 0.001) (p < 0.05)." (PMID 37197571, 2023). "Gestational age, C-reactive protein levels, and white blood cell count were important predictors to diagnose neonatal sepsis." (PMID 37386442, 2023).